STAT3 (signal transducer and activator of transcription 3)
Diseases named in the same sentence as STAT3 in open-access papers (continued):
Sharing a sentence is not in itself a finding about the gene and the disease.
cancer (continued). "NF-κB and STAT3 are two transcription factors that act synergistically and play crucial roles in both inflammation and cancer." (PMID 39834804, 2024). "Upon stimulation by GCSF, CD114 activates the transcription factor signal transducer and activator of transcription 3 (STAT3), which promotes a cancer stem cell (CSC) phenotype." (PMID 38474265, 2024). "This suggests that the crosstalk between NF-κβ and STAT3 signalling pathways drive cancer progression." (PMID 38600086, 2024). "Inhibition of constitutively STAT3 activation can induce apoptosis and inhibit cancer cell growth, indicating STAT3 is required for cancer cell survival and growth." (PMID 39000312, 2024). "Numerous novel targets have been identified, including SOCS, STAT3, Nrf2, NF-B, cell cycle regulators cyclin D1, D2, and D3, INPs, and Wnt, which are expressed improperly in pre-cancer lesions." (PMID 39246660, 2024). "Based on the crucial roles of STAT3 hyperactivation in cancer development and progression established in dozen studies over the past decades, STAT3 is undoubtedly an encouraging therapeutic target." (PMID 38245798, 2024). "Another pathway involved in the anti-neoplastic effects of metformin concerns STAT3 (signal transducer and activator of transcription 3), which is a promising cancer therapeutic target due to its crucial role in cell survival, proliferation, and migration." (PMID 38610965, 2024). "The signal transducer and activator of transcription 3 (STAT3) reacts to stress and is usually activated in many cancers, leading to cancer progression." (PMID 38674143, 2024). "The STAT3 signaling pathway participates in cell proliferation in several types of cancers, such as liver, breast, colorectal, gastric, and lung cancers." (PMID 38720012, 2024). "Napabucasin, an oral inhibitor of cancer stem cells acting by blocking STAT3 signaling, is being tested in various gastrointestinal tumors, either alone or in combination with standard chemotherapy." (PMID 39003350, 2024). "Specifically, in TNBC, studies have demonstrated that downregulating the JAK2/STAT3 pathway can significantly inhibit cancer stem cell proliferation." (PMID 38699644, 2024). "This is essential when studying complex signaling pathways like NF-κB and STAT3, which are involved in cancer progression." (PMID 39409068, 2024). "The ability of BP1003 to reduce the expression of STAT3 protein was assessed in human cancer cell lines." (PMID 39200368, 2024). "Mechanistically, myMAFs are induced through a STAT3-dependent mechanism driven by macrophage-derived progranulin and cancer cell-secreted leukaemia inhibitory factor (LIF)." (PMID 38678021, 2024). "Resveratrol, especially when combined with temozolomide, significantly inhibits STAT3 activation, reducing the expression of downstream effectors like Bcl-2 and survivin, which normally help cancer cells evade death." (PMID 39769099, 2024). "Napabucasin (NP) is a natural compound that can suppress cancer cell proliferation and cell cycle by inhibition of the signal transducer and activator of transcription 3 (STAT3) gene." (PMID 39356934, 2024). "Overexpressed MCT-1 stimulates the IL-6/IL-6R/gp130/STAT3 axis, which promotes epithelial-to-mesenchymal transition and cancer stemness." (PMID 38505617, 2024). "This suggests that it is possible that anlotinib exerts its inhibitory effect on cancer cell development by inhibiting the Jak-2/Stat3 signaling axis." (PMID 39193386, 2024). "STAT3 mediates the impacts of mTOR in macrophage-induced neoangiogenesis, potentially suggesting new insights into innate immune responses and new cancer therapy targets." (PMID 39003350, 2024). "HDAC6 is involved in PD-L1 expression through the STAT3 pathway, and its inhibition results in a reduction in PD-L1 expression in various types of cancer." (PMID 39063958, 2024). "STAT3 regulates the communication between cancer cells and immune cells and influences immune escape of tumors." (PMID 38464736, 2024).
cancer (continued). "Their findings revealed promising results, suggesting that garcinol targets the STAT3 signaling pathway, a key regulator of cancer progression." (PMID 39066940, 2024). "Our immunoprecipitation experiment indicates that USP21 directly interacts with STAT3 and positively regulates STAT3 expression level in cancer cells." (PMID 39305962, 2024). "This review summarizes current knowledge of the mechanisms of STAT3 pathway signaling as elucidated in in vitro and in vivo studies and discusses the role of constitutively activated STAT3 in cancer development." (PMID 38339245, 2024). "The interaction between the CXCL12/CXCR4/ACKR3 axis and the STAT3 signaling pathway is crucial in the development and progression of various diseases, including cancer." (PMID 38920657, 2024). "As such, treatment strategies targeting STAT3 in cancers should not only account for the state of STAT3-activation, but also address the dominant function of STAT3 in tumors." (PMID 38339245, 2024). "In our unpublished data indicates the IL‐17RA overexpression promotes cancer stem‐like properties of CRC cells by Stat3 activation." (PMID 38491831, 2024). "Signal transducer and activator of transcription 3 (STAT3) is one of the most crucial molecules activated during gastric carcinogenesis, driving chronic inflammation to cancer." (PMID 38481347, 2024). "Alantolactone suppressed muscle atrophy and adipocyte atrophy by inhibiting the STAT3 signaling pathway in cancer cachexia‐induced C2C12 and 3T3‐L1 cells and experimental mouse model." (PMID 38807976, 2024). "This is achieved by inhibiting the Notch1 and STAT3 signaling pathways, which are also involved in cancer cell proliferation." (PMID 38731894, 2024). "Cumulative pieces of evidence show that STAT3 plays critical roles in all steps of cancer metastasis including invasion, migration, and angiogenesis." (PMID 38245798, 2024). "Persistent phosphorylation of STAT3 has been commonly observed in various human cancers and plays a crucial role in supporting tumor survival and growth." (PMID 39451730, 2024). "Recent research has explored the relationship between miRNAs and STAT3 signaling in various cancers, revealing a close correlation." (PMID 38185635, 2024). "Multiple STAT3-activating cytokines can also be detected in the conditioned medium of primary cancer cells or cancer cell lines grown in vitro." (PMID 38611065, 2024). "Signal transducerand activator of transcription 3 (STAT3) is anattractive cancer therapeutic target." (PMID 38559310, 2024). "Given its role in regulating both normal and cancer stem cell functions, STAT3 is a promising target for cancer therapies." (PMID 39597836, 2024). "In certain circumstances, both activation of NF-κB and STAT3 promote pro-tumorigenic effects, including augmentation of cancer proliferation and anti-apoptotic gene expression." (PMID 38720012, 2024). "STAT3 is overexpressed in some cancerous tissues compared to its expression in normal tissues, and activated STAT3 promotes cancer growth and invasion." (PMID 38834900, 2024). "Using DLD1 and HCT15 CRC cells, resveratrol inhibited cancer growth by targeting the Akt/STAT3 signaling pathway." (PMID 37507626, 2024). "Crosstalk between SMAD3 and STAT3 has been demonstrated in numerous conditions, especially in cancer." (PMID 38902234, 2024). "The SOCS family of genes, which are important regulators of PIK3R3/STAT3 signaling, can be used to develop molecularly targeted drugs to inhibit PIK3R3/STAT3 signaling in a variety of cancers with unique modes of action." (PMID 39307915, 2024). "Our experimental results have shown that TP has the potential to be an effective anticancer agent by inhibiting essential signals that are involved in cancer cell proliferation, such as Notch1 and STAT3 signaling." (PMID 38731894, 2024). "The attachment of LIF to the JAK1 receptors on the surface of cancer cells can increase STAT3 and NF-κB expression." (PMID 39014491, 2024).
cancer (continued). "Manipulating the STAT3 pathway with PIAS holds promise for the treatment of cancers driven by aberrant STAT3 activity." (PMID 38590645, 2024). "Disturbance of mitochondrial function, ATP synthesis, and STAT3 phosphorylation observed in HAP-1 cells with genetically inactivated USP21 suggested that the fundamental features of cancer cells, such as proliferation and adhesion are regulated by USP21." (PMID 39305962, 2024). "miR-1181 can reduce the transcriptional activity of STAT3 and SOX2 by targeting the 3′-UTR of them in cancer pancreatic cells, and inhibit STAT3 trans activators." (PMID 38172648, 2024). "Reduced Ki-67 and cyclin D1 levels, as well as decreased phosphorylation of signal transducer and activator of transcription 3, occur in Il1r1Hep−/− livers, lowering cancer cell proliferation and growth." (PMID 39621069, 2024). "As demonstrated in previous studies, activated STAT3 promotes cancer cell metastasis through transcriptional activation of multiple mediators, including MMP2, MMP9 and EMT-related genes 51-53." (PMID 39113711, 2024). "It has been reported that MET is involved in regulating the cancer malignant phenotype by STAT3 and Akt." (PMID 38468814, 2024). "In cancer, STAT3 is involved in a complex network of signaling pathways (including NF-κB and IL-6) and alternative splicing events, resulting in the production of two isoforms: STAT3α and STAT3β." (PMID 39309860, 2024). "Overall, DARPP-32 overexpression has been recognized in more than 70% of cancers, while STAT-3 is phosphorylated and plays an important role in all steps of tumorigenesis." (PMID 39767693, 2024). "The downregulation of PIAS3 leads to the upregulation of STAT3, which promotes multiple oncogenic pathways; thus, it is an important target for cancer therapies." (PMID 38590645, 2024). "These endogenous inhibitors govern physiologic STAT3 function in normal cells and their activation is a potential therapeutic strategy in cancer cells with activated STAT3." (PMID 38339245, 2024). "The prominent role of JAK/STAT signaling, particularly STAT3 activity, in cancer development and progression across many types of tumors makes their activity a desired target for anticancer drug development." (PMID 38256080, 2024). "In cancer cells, one of the mechanisms by which constitutive STAT3 activation is initiated is by downregulation of endogenous regulators such as PTPs, PIAS, and SOCS." (PMID 38339245, 2024). "STAT3 is recognized as an oncogene, with dysregulated STAT3 activity reported in nearly 70% of cancers." (PMID 39121240, 2024). "iCAFs are the significant source of IL6 in the PDAC TME, with the ability to activate the STAT3 pathway in cancer cells." (PMID 39358777, 2024). "In accordance, the inhibition of STAT3 sensitizes cancer cells to radiation- and oxidative stress-induced DNA damage." (PMID 39001513, 2024). "STAT3 upregulates cancer cell-derived VEGF, and expression of GM-CSF is partially responsible for mTOR signaling." (PMID 38886756, 2024). "It interacts with tyrosine kinase (src) protein and activates signal transducer and activator of transcription 3 (STAT3) which is plays an important role in the signaling pathway of cancer progression." (PMID 39839775, 2024). "In vitro evidence supporting that Ruxolitinib induced decreases in cytokine levels and disruption of STAT3 activation via upstream signaling suggests a role for Ruxolitinib in cancer cases characterized by elevated IL-6 levels." (PMID 38339245, 2024). "The authors revealed that Napabucasin efficiently suppressed metastasis and relapse of a variety of cancers by inhibition of STAT3-driven gene transcription." (PMID 38326371, 2024). "As a supplement to these results, it was discovered that STAT3 can bind the RACGAP1 promoter to upregulate its transcription in multiple cancers." (PMID 39858398, 2024).
cancer (continued). "Prior findings of viral gene anticorrelation with MYC, STAT3, and BCL2A1 and lytic cell upregulation of cancer-associated stem-like pluripotency and host shutoff escapees were conserved in B958-ZHT." (PMID 38915538, 2024). "PKM2, a key player of the Warburg effect which is induced by HIF-1α, and STAT3 acts as HIF-1α/PKM2 feed-back loop participants which in turn enhances the Warburg effect in cancer." (PMID 38245798, 2024). "We also describe its cancer-promoting mechanisms from the perspective of the regulation of transcriptional factors, such as STAT3, and the influence on actin accumulation and mitosis via Rho-GTPases and GEF." (PMID 39858398, 2024). "STAT3 is a transcription factor whose constitutive activation in most of cancers drives cell survival and proliferation, e.g., by promoting the transcription of survivin, cyclinD1 and c-Myc." (PMID 39769907, 2024). "Further explanation of the mechanism of USP21-dependent STAT3 translocation to mitochondria, leading to mitochondrial protein translation, can significantly expand our understanding of cancer metabolism." (PMID 39305962, 2024). "We have discovered more than 50 inhibitors of STAT3 signaling so far and demonstrated that STAT3 is a good target to block the growth of various cancer cells." (PMID 38532948, 2024). "Chalcones hold promise as novel therapeutic agents targeting certain factors involved in the NF-κB and STAT3 signaling pathways in treating inflammatory diseases and cancer." (PMID 38539427, 2024). "Hyperactivation of STAT3 can effectively bypass the inhibitory effects of targeted therapeutic strategies against RTKs, increasing the resistance of cancer cells to RTK inhibitors." (PMID 39309860, 2024). "Activation and interaction between STAT3 and the NF-κB signaling pathway play a crucial communication role between cancer cells and inflammatory cells." (PMID 38957470, 2024). "Transcription factors play a critical role in regulating the expression of VEGF-A, with STAT3 known for its capacity to activate VEGF-A in cancer cells." (PMID 39198402, 2024). "In fact, evidence has shown a clear relationship between STAT3 levels and cancer chemotherapy resistance." (PMID 38555280, 2024). "There are also collaboration and crosstalk that occur between NF-κB and STAT3 in cancer progression, and efforts to target these pathways have yielded promising outcomes in cancer treatment." (PMID 38539448, 2024). "c-Met serves as an upstream regulator of STAT3, and its upregulation enhances the expression and phosphorylation of STAT3, which, when activated, can participate in the regulation of cancer proliferation and metastasis." (PMID 39840050, 2024). "TNF-α activates the signal transducer and activator of transcription 3 and NF-kB, promoting cancer growth." (PMID 39099698, 2024). "Radiation-resistant cancer cells have been found to feature high levels of nuclear expression of STAT3, and some studies suggested that the inhibition of this pathway can reverse the EMT process, thus overcoming radio resistance." (PMID 38781107, 2024). "Accumulating evidence suggest that the Janus kinases (JAKs) and signal transducer and activator of transcription (STAT) proteins, particularly STAT3, are among the most promising new targets for the treatment of cancer." (PMID 37950040, 2024). "In lung cancer, IL-6 mediates interactions between cancer cells and microglia via Jak2/STAT3 signaling, aiding brain metastasis, a significant mortality driver." (PMID 39286635, 2024). "In summary, YY002 selectively inhibitedpancreatic cancer cell proliferation and suppressed STAT3 Tyr705 andSer727 phosphorylation." (PMID 38559310, 2024). "Research has shown that TP can limit STAT3 phosphorylation, thereby reducing STAT3-mediated gene expression and affecting the proliferation and survival of cancer cells." (PMID 38731894, 2024).
cancer (continued). "STAT3 is a critical transcription factor involved in cancer migration and invasion, and it is commonly utilized as a biomarker for poor cancer prognosis." (PMID 38397971, 2024). "AZD9150 is a second-generation antisense oligonucleotide targeting the 3′-untranslated region (3′-UTR) of the STAT3 gene with reduction in STAT3 expression noted in a variety of preclinical cancer models." (PMID 38339245, 2024). "While in vitro evidence indicates that STAT3 lacks classical driver properties, it nevertheless plays an essential role in cancer maintenance and epithelial-mesenchymal plasticity." (PMID 38573819, 2024). "This concurs to increase the recruitment of STAT3 enhancing tyrosine phosphorylation increasing cancer progression." (PMID 38650006, 2024). "Another natural compound, Curcumin, enhances PIAS3 expressions and inhibits STAT3 phosphorylation in ovarian and endometrial cells in cancer." (PMID 38590645, 2024). "Activation of STAT3 and upregulation of MCL1 have been previously associated with cancer cell survival and resistance to cell death." (PMID 38485916, 2024). "Napabucasin is an original molecule discovered to phosphorylate and suppresses the signal transducer and activator of transcription 3 (Stat3) up to pStat3, which controls important mechanisms such as growth, proliferation, and survival of cancer cells." (PMID 39356934, 2024). "Signaling kinases associated with cancer progression, which are easily activated by IL-8, include MAPK, FAK, and Src, along with NF-kB, PI3K/Akt, and Jak2/STAT3/SNAIL pathways." (PMID 39201656, 2024). "Conversely, increased ECM stiffness can promote cancer cell immune evasion by promoting the activation of the STAT-3 pathway, a consequence of elevated SNF5 expression." (PMID 38693104, 2024). "CCL3 and CCL4 can also be produced by MDSC and TAMs themselves, leading to both autocrine and paracrine STAT3 activation and subsequent enhancement of cancer cell proliferation, invasion, and epithelial–mesenchymal transition." (PMID 38108458, 2024). "Inhibiting GP130/STAT3 signaling with BZA can sensitize these cancer cells to treatment, thereby reducing cell viability and inducing apoptosis." (PMID 39451730, 2024). "PRMT5 expression is also induced by STAT3, suggesting the presence of a positive feedback loop in cancer cells." (PMID 38760429, 2024). "Studies related to its molecular mechanisms have shown that TP can regulate the STAT3 pathway, which is frequently activated in cancer and is a potential target for cancer therapy." (PMID 38731894, 2024). "During the progression and metastasis of malignant tumors, STAT3 undergoes persistently activation in response to continuous growth signals." (PMID 39508048, 2024). "This is because the IL-6/STAT3 signaling pathway is activated in many chronic inflammatory diseases, such as cardiovascular disease and cancer." (PMID 38617550, 2024). "A large number of studies currently indicate that STAT3 plays an important role in mediating drug resistance in cancer treatment." (PMID 38172648, 2024). "Research has elucidated that the JAK2/STAT3/Cyclin D2 signaling pathway is pivotal in promoting cancer stem cell proliferation." (PMID 38699644, 2024). "These apoptotic effects are stimulated via the inhibition of the transducer and activator of transcription 3 (STAT-3), a transcription factor crucial in tumorigenesis and cancer progression." (PMID 39409552, 2024). "Our research suggests that TP can hinder the growth of cancer cells by inhibiting the signaling pathways of Notch1 and STAT3." (PMID 38731894, 2024). "The activated Notch1 receptor increases the level of phosphorylated STAT3, promoting cancer progression in gastric cancer." (PMID 38611065, 2024). "Studies have shown that it can inhibit the activation of STAT3 in cancer cells, enhance drug sensitivity, and prevent drug resistance against targeted therapy and chemotherapy." (PMID 38822350, 2024).